MIR1255B1 (microRNA 1255b-1)
Synonyms: hsa-mir-1255b-1; MIR1255B-1; MIRN1255B1
Gene: MicroRNA gene on chromosome 4 (36,426,366 to 36,426,428, reverse strand). Ensembl gene ENSG00000283207.
Gene Ontology:
Biological process: miRNA-mediated post-transcriptional gene silencing